INS (insulin)
Diseases named in the same sentence as INS in open-access papers (continued):
Sharing a sentence is not in itself a finding about the gene and the disease.
diabetes (continued). "The rate of use of hypoglycaemic agents in combination with insulin was higher in patients with DN than in those without DN, indicating that there exists an association between poor diabetes control and DN." (PMID 36348847, 2022). "The insulin clearance with the polysulfone membrane, however, was significantly higher than with the other two membranes, and a significantly higher plasma insulin reduction ratio was observed with the polysulfone membrane in insulin-dependent diabetes mellitus subjects." (PMID 35329847, 2022). "Furthermore, the modulation of Drp1, observed in the hippocampus of a mouse model of diabetes by Gsk3β, confirms the role of insulin signaling in mitochondrial dynamics." (PMID 35741464, 2022). "On the other hand, high free fatty acids in the liver may cause fasting hyperglycemia, hyperinsulinemia, and decreased insulin signaling, which eventually leads to diabetes." (PMID 35549705, 2022). "Nearly all insulin-treated patients with diabetes utilize basal insulin, and while there are pharmacokinetic (PK) and potency differences across available basal insulins, all are full agonist insulin analogs, as is also true for the rapid acting insulin analogs." (PMID 35177603, 2022). "Type 2 Diabetes Mellitus (T2DM) is the main type of diabetes in adults, which is characterized by a gradual deterioration of glycemic control due to progressive pancreatic beta-cell dysfunction of insulin secretion on the background of increasing of insulin resistance." (PMID 35617250, 2022). "Furthermore, there are reports that insulin regulates Aβ and tau protein metabolism, and there are numerous reviews discussing the established connections between insulin resistance, diabetes, and AD7,12–14." (PMID 35927256, 2022). "It suggests, appropriate blood glucose-lowering treatment in patients with overt diabetes, and the prevention or delay of diabetes onset by eliminating high insulin demand among the prediabetes population, may benefit the reduction of cancer risk." (PMID 35256755, 2022). "Diabetes mellitus (DM) is characterised by diminished insulin availability, action, or both." (PMID 35682865, 2022). "Indeed, diabetes is a metabolic and nutritional pathology, it occurs as a result of a defect in insulin secretion, insulin action or both." (PMID 35291359, 2022). "In addition, UCMSCs can differentiate into functional islet cells, which can contribute to the release of physiological insulin as well as C-peptide, thereby holding promise as a therapeutic agent for the treatment of diabetes." (PMID 36514009, 2022). "Diabetes onset also perturbed β-cell function and insulin resistance indices, damaged pancreas microanatomy, while disrupting the expression of insulin receptor substrate 1 (IRS-1), phosphatidylinositol 3-kinase (PI3K), protein kinase B (AKT) and glucose transporter isoform 4 (GLUT-4) mRNA." (PMID 35739183, 2022). "In addition, the oral administration of C. officinalis protected against damage to diabetes-induced pancreas and kidney injury, increased the pancreas’s beta cells, and consequently increased insulin levels." (PMID 35563963, 2022). "The current pharmacotherapy for diabetes involves insulin secretagogues, insulin sensitizers, alpha-glucosidase inhibitors, biguanides, incretin mimetics, sodium-glucose co-transport-2 inhibitors, amylin antagonists, and insulin." (PMID 36545334, 2022). "Diabetes management is complex and insulin treatment in particular, people with intellectual disabilities may require additional support that is not always available." (PMID 35983585, 2022). "Studies have demonstrated a protective effect of butyrate by improving body weight, blood glucose, lipid distribution, and insulin sensitivity in animal models of obesity and diabetes, which can be postulated as new therapeutic strategy to counteract obesity and insulin resistance." (PMID 36016798, 2022).
diabetes (continued). "Type 1 diabetes (T1D) also known as insulin-dependent diabetes mellitus is an autoimmune condition characterized by inflammatory responses due to the influx of immune response cells in the pancreas, leading to the destruction of insulin-producing beta cells." (PMID 35668933, 2022). "Increased SUA levels may promote the occurrence and development of diabetes by inflammation, oxidative stress, vascular endothelial injury, and inhibiting insulin pathway." (PMID 36464722, 2022). "While certain types of insulin and particular dosing strategies demonstrate some advantages, these recommendations should be tailored to the context of each person with diabetes to make the appropriate regimen adjustments in preparation for intensive fasting practices during the month of Ramadan." (PMID 35634376, 2022). "For example, diabetes management requires self-monitoring of blood sugar levels several times a day (via fingertip lancing), insulin injections and oral medications, care for lower limbs, adequate physical activity, and close monitoring of diet, all of which can be quite stressful for patients." (PMID 35145767, 2022). "The use of TZDs as an add-on to insulin in T1D is limited to some small studies which were largely not able to demonstrate positive effects on diabetes-related endpoints or further cardiovascular risk factors." (PMID 35745754, 2022). "In general, several treatment strategies have been employed based on the type of diabetes, for instance, direct administration of insulin for type-1 diabetes and delivery of various therapeutics promoting the insulin release from the β-cells of the pancreas for type-2 diabetes." (PMID 35279150, 2022). "An active compound that can help induce insulin intake and reduce blood sugar levels in blood remained to be the goal in diabetes treatment along with reducing diabetes complications such as heart attacks, kidney failure, limb amputation, blindness, and stroke." (PMID 35954003, 2022). "Our data suggest that metformin and rosiglitazone attenuate the depletion of the β-cell pool in the streptozotocin-induced diabetes, whereas tolbutamide exacerbates the β-cell apoptosis, but is likely to protect β-cells from chronic hyperglycaemia by directly elevating insulin secretion." (PMID 34191257, 2022). "Description of variables related to the time factor for ESRD, diabetes, and insulin intake." (PMID 35475809, 2022). "Diabetes mellitus (DM) is a chronic metabolic and degenerative disorder that is characterized by chronic hyperglycemia resulting from defects in insulin action due to insulin resistance, insulin secretion, or both." (PMID 36443718, 2022). "Type 2 diabetes mellitus is linked to chronic low-grade systemic inflammation and oxidative stress in β-cell, leading to low or no insulin secretion due to a loss of β-cells." (PMID 35954249, 2022). "Yoga practices are believed to increase insulin production and thus help in controlling diabetes." (PMID 36120271, 2022). "Recognising insulin as a lifelong therapy also may be related to patients’ perceived chronicity of diabetes." (PMID 35172774, 2022). "However, for patients with non–insulin-treated diabetes mellitus type 2 (DMT2), the value of SMBG was inconsistent among studies, and the evidence for digital technologies from real-world clinical practice is still limited." (PMID 35704371, 2022). "Mean diabetes duration differed radically, due to the acute trial participants having type 1 diabetes, and the long-term type 2 diabetes (39 ± 16 years vs. 16 ± 5 years), as did insulin use, for the same reason (100 vs. 66%)." (PMID 35571091, 2022). "Diabetes medications included insulin analogs (15%) and oral glucose-lowering drugs." (PMID 36143914, 2022). "The use of natural compounds as insulin sensitizers may thus have significant benefits in the treatment of diabetes." (PMID 36678512, 2022).
diabetes (continued). "Of the 8 studies, 4 (50%) provided diabetes-related complications, including retinopathy, neuropathy, and nephropathy; 6 (75%) reported that 1.6% to 100% of the participants injected insulin; and 6 (75%) reported 4.4% to 100% sulfonylureas use." (PMID 35576579, 2022). "Disturbances in sleep architecture or sleep restriction may decrease insulin sensitivity and worsen diabetes compensation, thus inadequate amount of sleep has been linked to weight gain." (PMID 35784568, 2022). "If it persists on time, it can lead to the development of metabolic syndrome, NAFLD, cardiovascular diseases (CVD), Alzheimer’s disease (AD) and, most commonly, when β-cells cannot keep up and insulin production gradually decreases until it stops, type 2 diabetes mellitus (T2DM)." (PMID 35204710, 2022). "The regeneration and transplantation of islet β cells and the reconstruction of insulin secretion function have become new strategies for curing diabetes, but the donor and site of transplantation and the selection of transplantation carriers are the key to this strategy." (PMID 35845408, 2022). "Diabetes in its two main forms is characterized by an absolute or relative insulin deficit." (PMID 35185804, 2022). "In addition, weekly exercise training in this model was also effective in reducing the incidence of diabetes, increasing pancreatic beta-cells volume and insulin content, improving beta-cell mass, and reducing connective tissue in the pancreas." (PMID 35742478, 2022). "Several clinical studies have indicated that FCM consumption can lower cholesterol and improve lipid profile which might help control insulin levels and attenuate diabetes complications." (PMID 35453353, 2022). "Instead, a study in black Americans with the same type of diabetes demonstrated that visceral but not subcutaneous abdominal fat volume was associated with insulin resistance." (PMID 36614099, 2022). "However, when β-cells are exposed to chronic hyperglycemia after the onset of type 2 diabetes mellitus, β-cell function gradually deteriorates due to overwork for insulin biosynthesis and secretion." (PMID 35453568, 2022). "Diabetes is related to alterations in glucose homeostasis governed by insulin." (PMID 36142518, 2022). "The CV health study in adults aged ≥ 65 years showed that the CHD-associated mortality in persons with diabetes either treated with oral agents or insulin was more than twice as high as those without." (PMID 35831938, 2022). "In addition, high SUA levels can directly damage pancreatic β cells, leading to impaired pancreatic β cell function, reduced insulin synthesis, glucose metabolism disorder, and induced diabetes." (PMID 36498206, 2022). "Together, these data support the concept that elevation of TGS1 levels in β-cell and insulin-sensitive tissues could be a common marker of hyperglycemia/insulin resistance in diabetes." (PMID 35041827, 2022). "This suspicion of malignancy may require resection procedures and most of the patients with symptoms are diabetic at the time of surgery and are on insulin for the control of diabetes mellitus." (PMID 35273837, 2022). "Diabetes occurs in part because the accumulation of triggered innate immune cells leads to the release of inflammatory markers, principally IL-1β and tumor necrosis factor α, that promote generalized resistance to insulin and destruction of β-cell." (PMID 35975270, 2022). "Taken together, our results provide a strong link between impaired PI3K activity and genomic instability, a crucial relationship that needs to be monitored not only in diabetes due to impaired insulin signaling but also in cancer therapies based on PI3K inhibitors." (PMID 35678366, 2022). "Patients with “burnt-out diabetes’ often require only low-dose insulin treatment." (PMID 35528010, 2022). "One had come off insulin onto oral medication and a diet to manage her diabetes." (PMID 40496687, 2022).
diabetes (continued). "Therefore, patients with diabetes share common characteristics, mainly raised blood sugar levels, decreased insulin sensitivity, obesity, dyslipidemia and hypertension, which almost always appear simultaneously." (PMID 36555184, 2022). "Thus, we assume that the modulation of insulin action and triglyceride levels will be beneficial for the treatment of both hypothyroidism and diabetes-related dementia." (PMID 35328405, 2022). "Specifically, Mt remodeling in hypertensive and insulin-resistant lean models (Ren2 rat models), lean mice with streptozotocin-induced diabetes, obesity models including diet-induced obesity, genetic leptin-deficient ob/ob, and leptin receptor-deficient db/db diabetic mice are examined." (PMID 35563211, 2022). "In particular, publications involving insulin pumps were excluded because their effects on glycemic management may have altered the development of diabetes complications above that of the effect of CGM alone." (PMID 35094087, 2022). "Insulin is the main medication used in the treatment of diabetes mellitus." (PMID 35056780, 2022). "Furthermore, the blood glucose and AUC of the mice in the diabetes model group exceeded the values in the normal group (p < 0.05) after insulin injection." (PMID 38647883, 2022). "Metformin is a potent insulin-sensitizing drug for the treatment of diabetes mellitus." (PMID 35841070, 2022). "INS gene biallelic mutations are the second most common cause of permanent neonatal diabetes mellitus after the ATP-sensitive K+ (KATP) channels defects, instead INS monoallelic mutations are implicated in a rare MODY subtype (INS-MODY or MODY 10), (MIM # 613370), especially in European countries." (PMID 35769090, 2022). "Therefore, mulberry total biotobasine promotes insulin secretion and ameliorates the β cells of diabetes rats’ dysfunction and mass reduction both in vivo and in vitro." (PMID 36760813, 2022). "However, there is evidence that diabetes patients treated with insulin sensitizers including metformin and thiazolidinediones can develop prostate and breast cancers." (PMID 35408706, 2022). "This multifaceted relationship between diabetes milieu and sleep breathing is based on several pathophysiological mechanisms that include insulin resistance, inflammatory and oxidative stress-activated signaling pathways, leptin resistance and abnormalities in the autonomic nervous system." (PMID 35268504, 2022). "There were no time or group × time interactions observed for either word list recognition and Trails B minus A. Similarly, the results remained unchanged in an additional model after adjustment for age, sex, educational level, insulin usage, duration of diabetes, HbA1c, and MMMSE at baseline." (PMID 35436329, 2022). "Diabetes mellitus (DM) is a chronic metabolic disorder that affects an increasing number of people globally and is characterized by elevated blood glucose (hyperglycemia) and elevated blood insulin (hyperinsulinemia)." (PMID 36359733, 2022). "For example, insulin, the glycemic index (GI), and other concepts about diabetes could be added to the analytical framework." (PMID 36115943, 2022). "Although these mutations result in reduced insulin action and in compensatory increased circulating insulin, these mutations do not result in hyperglycemia or diabetes." (PMID 34863942, 2022). "The insulin-releasing action of these drugs can be persistent at low glucose levels, which would lead to the development of hypoglycemia, making these drugs an undesirable choice for older patients with diabetes." (PMID 35055382, 2022). "For instance, in experimental studies in rats, pinealectomies led to increased bodyweight, impaired glucose tolerance, and elevated insulin levels, whereas melatonin substitution in diabetes-prone rats prevented the development of diabetes and was even able to reduce bodyweight." (PMID 35140394, 2022).
diabetes (continued). "Type 2 diabetes mellitus (non-insulin-dependent diabetes) is a multifactorial disease caused by impaired insulin secretion, abnormalities in its action on target tissues, or a combination of both." (PMID 35655685, 2022). "Additionally, Akbarzadeh and co-workers supported that the blood glucose level, food and water consumption, and urine volume were markedly increased, while the body weight and insulin level were reduced, following streptozotocin-induced diabetes in rats." (PMID 36144807, 2022). "Combinations of antiviral therapy given after T1D onset could also reverse symptoms of diabetes in conjunction with the disappearance of viral antigen from the insulin-producing β-cells." (PMID 35336174, 2022). "It cannot escape the attention that insulin pen injectors may help not only patients but also diabetes care teams." (PMID 35355552, 2022). "In the case of cardiogenic shock, aortic thrombosis, epileptic seizures, muscle tremors, renal liver failure, decompensated diabetes, neoplastic disease, intoxication with ethanol, glycol, insulin, morphine, salicylates, and other drugs, an increase in lactate levels is observed." (PMID 36012398, 2022). "This may be the result of a longer period of development of diabetes in women: women are more insulin-sensitive in middle age, and their insulin sensitivity deteriorates more than in men before they reach the diagnosis of diabetes." (PMID 35837485, 2022). "In addition to diabetes and alcohol drinking, which were examined in this study, obesity and diabetes medications such as insulin should be considered." (PMID 35565424, 2022). "The outcomes of this study emphasize the importance of hepatic glycogen for diabetes management, and the ligand-switchable Pep/Gal-PNPs may represent a significantly improved oral insulin therapy." (PMID 36333321, 2022). "While, in type 1 diabetes mellitus (T1DM), destruction of pancreatic islet beta-cells leads to insufficient insulin levels, type 2 diabetes mellitus (T2DM) is caused by insulin resistance driven by genetic predisposition, obesity or poor nutrition and insufficient insulin secretion." (PMID 36190648, 2022). "The development of oral insulin delivery methods has been a breakthrough in diabetes treatment." (PMID 35055294, 2022). "Although not reported in humans, insulin amyloidosisin the islets of the pancreas causing diabetes has been noted in therodent degu (Octodon degus), found in Chile." (PMID 36407954, 2022). "In addition, blood glucose critical values and glycemic excursion were monitored for multiple times in hospital despite insulin treatment, implicating very poor control of diabetes." (PMID 35787271, 2022). "Another study showed that flaxseed intake could reduce blood glucose and insulin levels and increase insulin sensitivity in overweight and obese people with pre-diabetes." (PMID 35144649, 2022). "In addition, two of the top five frequently used PIMs were related to diabetes (insulin [sliding scale] of androgens and sulfonylureas), for a higher exposure of PIMs in older people with diabetes." (PMID 36203703, 2022). "However, it is important to note that insulin is also necessary in some older patients with diabetes." (PMID 36249753, 2022). "Patients in the insulin group were older and had diabetes longer as compared to the OAH group." (PMID 35482748, 2022). "Low blood pH could reduce the uptake of glucose by muscle tissue, disrupt the binding of insulin to its receptors, and further inhibit insulin signaling pathways, which could lead to the development of insulin resistance and diabetes." (PMID 35694169, 2022). "Diagnosis: new coronavirus infection COVID-19 of severe severity, community-acquired bilateral pneumonia of severe severity, respiratory failure of the third degree, CT-4 (80% lung damage), type 2 diabetes mellitus, insulin-dependent, unspecified erythrocytosis." (PMID 36883180, 2022).